CYP2D6 (cytochrome P450 family 2 subfamily D member 6 (gene/pseudogene))
Diseases named in the same sentence as CYP2D6 in open-access papers (continued):
Sharing a sentence is not in itself a finding about the gene and the disease.
atrial fibrillation (4 papers, 2023 to 2025). A disorder characterized by an electrocardiographic finding of a supraventricular arrhythmia characterized by the replacement of consistent P waves by rapid oscillations or fibrillatory waves that vary in size, shape and timing and are accompanied by an irregular ventricular response. "Another report described a 43-year-old man who developed new-onset atrial fibrillation during rapid aripiprazole titration, potentially influenced by cardiovascular comorbidities, CYP2D6 polymorphism, and concurrent medications." (PMID 40792205, 2025). "This study explores the association between the efficacy of diltiazem and the genetic polymorphism of CYP2D6 in patients with atrial fibrillation with rapid ventricular response." (PMID 37326775, 2023). "Recent case reports found an association between CYP2D6 activity and atrial fibrillation or abnormal heart electrophysiology, suggesting that CYP2D6 genetic variants affecting this enzyme activity should be considered in future studies." (PMID 38375208, 2023). "The aim of our study is to evaluate the relationship between CYP2D6 gene polymorphism and the efficacy of diltiazem, which is used in the acute retarding treatment of patients who present to the emergency department with atrial fibrillation with rapid ventricular response." (PMID 37326775, 2023).
delirium (4 papers, 2015 to 2025). A disorder characterized by confusion; inattentiveness; disorientation; illusions; hallucinations; agitation; and in some instances autonomic nervous system overactivity. "PK interaction with paroxetine, a potent inhibitor of CYP2D6, has been reported in healthy volunteers who had the CYP2D6*10 allele, which is frequent in Asians with clinical consequences (flecainide-induced delirium)." (PMID 25870032, 2015). "As a consequence of the suicide attempt with overdose and the chronic paroxetine treatment that preceded it, phenoconversion to a poor metabolizer with very low CYP2D6 enzyme activity is suggested as contributing to an extremely long intoxication accompanied by delirium." (PMID 39295933, 2024).
Dystonia (4 papers, 2014 to 2022). An abnormally increased muscular tone that causes fixed abnormal postures. "We theorize that CYP2D6 governs the risk of metoclopramide-related acute dystonia through its role in the synthesis of serotonin, which inhibits the dopamine tone." (PMID 31507424, 2019). "Initial symptoms of the patient might be also related to the abuse of dextromethorphan- and pseudoepedrine-containing remedies as both medications are metabolized by CYP2D6 and known to cause dystonia and psychotic symptoms." (PMID 24253372, 2014). "Their case series also mentioned the case of a 14-year-old female, CYP2D6 *4/*41 (PM), who presented numerous ADRs, including EPS, akathisia, and dystonia, when treated with clozapine and loxapine." (PMID 35745668, 2022).
injury (4 papers, 2016 to 2025). Damage inflicted on the body as the direct or indirect result of an external force, with or without disruption of structural continuity. "In this study, we investigated the effect of Hippophae rhamnoides L. (HRP) on the activity of CYP2D6 via the CAMP/PKA/NF-κB pathway in rats with Bacille Calmette–Guerin (BCG)-induced immunological liver injury." (PMID 37833431, 2023). "In this case, the fast metabolic characteristics of VEN lead to a high abundance of cytochrome isoenzymes (mainly CYP2D6 and CYP2C19) as well as rapidly accumulated O-desmethylvenlafaxine, which are thought to be involved in VEN-associated liver injury." (PMID 34889278, 2021). "CYP2D6*10 homozygosity was found in 33.3% (1/3) of patients with antidepressant-induced liver injury, but only in 7.8% (9/116) of patients with an available LFT." (PMID 27171561, 2016). "In this study, we evaluated the changes in metabolic activity and protein expression of CYP2D6 and the effect of HRP on the cAMP/PKA/NF-κB pathway in an immune-mediated liver injury rat model obtained by injecting BCG into the tail vein of rats." (PMID 37833431, 2023).
liver dysfunction (4 papers, 2003 to 2025). "Oxymorphine, the active metabolite of oxycodone, is formed in a reaction catalysed by the cytochrome isoenyme CYP2D6, which is under polymorphic, genetic control and severely impaired by liver dysfunction." (PMID 14647133, 2003).
melanoma (4 papers, 2015 to 2022). A malignant, usually aggressive tumor composed of atypical, neoplastic melanocytes. "As a melanoma-associated gene, CYP2D6 were also possibly involved in the development of HVP occurring in chicken with two significant variations (rs314284996 and rs317955795) in the promoter regions." (PMID 35299951, 2022). "Numerous research groups have shown that individuals with polymorphisms that cause defective CYP2D6 are at increased risk for melanoma." (PMID 31024618, 2019). "Interestingly, CYP2D6 was identified as a biomarker associated with increased susceptibility to melanoma, which is coded for another enzyme that may play a role in detoxifying potentially carcinogenic compounds." (PMID 35299951, 2022). "Considering that high frequency of polymorphisms of CYP2D6 or the polymorphism of VDR, and null for GSTM1 gene in melanoma patients, it is plausible that changes in GSTM1, CYP2D6 and VDR genes may increase the risk for both PD and melanoma." (PMID 26535116, 2015).
mood disorder (4 papers, 2022 to 2025). A cognitive disorder a disturbance in which the person's mood is hypothesized to be the main underlying feature. "Genotyping for CYP2D6 and CYP2C19 variants in the context of specialized mood disorder services that offer tailored interventions to complex patients is suggested here as an additional supportive approach to complement available innovative technologies." (PMID 37490261, 2023). "Also, the predominance of women in CYP2D6 testing could possibly relate to higher instances of mood disorders in the female population and their awareness of pharmacogenetic factors affecting treatment efficacy." (PMID 40573293, 2025).
neuroblastoma (4 papers, 2018 to 2024). Neuroblastoma (NB) is the most common solid, extracranial childhood tumor. "In addition, the CYP2D6 gene is positively regulated by PPARγ, as shown in vitro in neuroblastoma SH-SY5Y cells and in vivo in the cerebellum and liver of mice." (PMID 36359909, 2022). "However, the expression of the four isoforms in general can vary depending on the brain area and cellular type, and the only expression of CYP2D6 at mitochondrial level highlights the importance of this isoform only in neuroblastoma SH-SY5Y cells." (PMID 30373287, 2018). "The evidence of the induction of CYP2D6 in SH-SY5Y cells, in conflict with that observed in hepatocytes, suggests that this isoform has a different regulation in the neuroblastoma cell line." (PMID 30373287, 2018).
opioid use disorder (4 papers, 2021 to 2025). A substance-related disorder that involves the recurring use of opioids despite negative consequences. "Our aim was to analyze the potential impact of CYP2D6 phenotypes and sex on the clinical and safety outcomes during an opioid use disorder (OUD) tapering process." (PMID 37324467, 2023).
adenovirus infection (3 papers, 2020 to 2022). "In addition, an improved method of CYP2D6-induced AIH mouse model was established by initial disposable adenovirus infection and repeated injection of human CYP2D6 plasmids using hydrodynamic liver-targeted gene delivery technology." (PMID 35721478, 2022). "Recently, we also introduced an improved method for establishing a CYP2D6-induced AIH mouse model using an initial one-time adenovirus infection and repeated injections of human CYP2D6 plasmid based on the hydrodynamic-based liver-targeted gene delivery technique." (PMID 33117375, 2020).
anaemia (3 papers, 2019 to 2022). "Updated information was generated on the prevalence of anaemia and the different G6PD and CYP2D6 variants in the target population." (PMID 31234865, 2019). "Twenty-four percent (15/62) of CYP2D6 EM/UM G6PDd individuals experienced moderate anemia, compared to 23% (11/48) of CYP2D6 PM/IM G6PDd individuals (adjusted odds ratio, 2.11 [95% CI, 0.46, 9.72]; P = 0.334)." (PMID 31383656, 2019). "Only one G6PDd individual from Burkina Faso had severe anemia after PQ treatment (Hb concentration of 7 g/dl at day 10); this individual was CYP2D6 EM/UM, had a baseline Hb concentration of 12.5 g/dl, and recovered completely by day 14 (Hb concentration of 11.9 g/dl)." (PMID 31383656, 2019). "At the enrolment 39.4% (13/33) and 58.1% (72/124) of patients with reduced and normal CYP2D6 enzyme activities had anaemia, but the prevalence of anaemia was not significantly different between the status (x2 = 3.659, p = 0.056)." (PMID 35279143, 2022). "However, some evidence of a reassuring safety profile in the broader target population was generated by defining the prevalence of anaemia and G6PD/CYP2D6 genotypes among all those screened." (PMID 31234865, 2019). "However, the prevalence of patients with anaemia at the enrolment and on days 3 and 7 following the initiation of treatment were not statistically significantly different between the CYP2D6 status." (PMID 35279143, 2022).
attention deficit-hyperactivity disorder (3 papers, 2021 to 2024). A disorder characterized by a marked pattern of inattention and/or hyperactivity-impulsivity that is inconsistent with developmental level and clearly interferes with functioning in at least two settings (e.g. at home and at school). "Integrating CYP2D6 genotyping and therapeutic drug monitoring (TDM) is crucial for guiding individualized atomoxetine therapy in children with attention-deficit/hyperactivity disorder (ADHD)." (PMID 38504095, 2024).
Cognitive impairment (3 papers, 2020 to 2023). Abnormal cognition is characterized by deficits in thinking, reasoning, or remembering. "Higher CYP2D6 metabolism was associated with high positive and high cognitive impairment groups relative to low symptom severity groups." (PMID 37763122, 2023). "Higher CYP2D6 activity scores were associated with high positive symptoms (p = 0.01) and high cognitive impairments (p = 0.0005) as compared to low symptom severity groups." (PMID 37763122, 2023). "Similarly, another study found that carriers of the CYP2D6*4 allele (NM) were associated with cognitive impairments, suggesting CYP2D6 genotype may moderate cognition." (PMID 37763122, 2023). "While these PRSs did not significantly associate with clinical and cardiometabolic outcomes, higher CYP2D6 activity scores were found to play a role in high positive symptom and high cognitive impairment trajectories as compared to low symptom severity groups." (PMID 37763122, 2023). "Individuals with high CYP2D6 activity scores had 1.46 and 2.53 greater odds of experiencing positive symptoms and cognitive impairments, respectively, as compared to those without impairments." (PMID 37763122, 2023).
Gaucher disease type 1 (3 papers, 2019 to 2021). Gaucher disease type 1 is the chronic non-neurological form of Gaucher disease (GD; see this term) characterized by organomegaly, bone involvement and cytopenia. "Eliglustat is an oral therapy approved in the European Union (2015) and the United States (2014) as a first-line treatment for adults with type 1 Gaucher disease who have compatible CYP2D6 metabolism phenotypes." (PMID 33639165, 2021). "Eliglustat is a first-line oral treatment for adults with Gaucher disease type 1 who have an extensive, intermediate or poor CYP2D6 metabolizer phenotype (> 90% of patients)." (PMID 31174576, 2019). "Eliglustat is indicated for adult patients with Gaucher disease type 1 (GD1), who are CYP2D6 poor metabolisers (PMs), intermediate metabolisers (IMs) or extensive metabolisers (EMs) and thus should be genotyped for CYP2D6 to determine the CYP2D6 metaboliser status." (PMID 34790681, 2021).
Gynecomastia (3 papers, 2018 to 2023). Abnormal development of large mammary glands in males resulting in breast enlargement. "We hypothesize that the inhibition of CYP2D6 increased the concentration and side effects of venlafaxine (hyponatremia; additionally associated with the inhibition of CYP3A4), mianserin (restless legs syndrome), and paroxetine (gynecomastia/mastalgia)." (PMID 37829299, 2023).
Hepatitis (3 papers, 2004 to 2023). Inflammation of the liver. "Our experimental findings showed that in the phase of inflammation regression, HRP inhibited NF-κB by upregulating PKA activated by cAMP and inhibited TNF-α and IL-1β, which resulted in liver inflammation regression and restoration of damaged CYP2D6 and liver function." (PMID 37833431, 2023). "The gradient changes in IL-1β, TNF-α, NF-κB, cAMP, PKA, CREB, and CYP2D6 during the inflammatory process, along with the occurrence and remission of inflammation, suggest that IL-1β may be involved in the pathological process of hepatitis." (PMID 37833431, 2023). "For instance, CYP1A2 is the molecular target in dihydralazine-induced hepatitis and AIH as a component of APECED, CYP2D6 in AIH-2 and in some patients with HCV infection, CYP2A6 in APECED and in a proportion of patients with HCV infection and UGT1 in some cases of AIH-2 and chronic hepatitis D or C." (PMID 15679907, 2004).
insomnia (3 papers, 2022 to 2024). A sleep disorder characterized by difficulty in falling asleep and/or remaining asleep. "Traits that were linked to CYP2D6 were the levels of metabolites, response to a drug, insomnia, and brain function." (PMID 39457450, 2024). "Last, one last RCT reported an increase in the occurrence of increased alkaline phosphatase, sweating, and insomnia in CYP2D6 poor metabolizers (PM) compared to extensive metabolizers (EMs)." (PMID 37857898, 2024).
leukaemia (3 papers, 2008 to 2025). "Finally, the possible association between the CYP2D6*4 polymorphism and the etiology of childhood leukemia was also demonstrated; however, these findings are conflicting and have already been discussed in the literature." (PMID 40276105, 2025).
opioid dependence (3 papers, 2020 to 2025). "The prior study focused on existing users of CYP2D6-metabolized opioids who likely developed opioid dependence at baseline." (PMID 40455735, 2025).
prostate carcinoma (3 papers, 1998 to 2022). A carcinoma that arises from epithelial cells of the prostate gland. "In final step, literature mining was used to uncover and visualise the relationships between splice-disrupt variants, genes, clinical parameters, diseases, and chemicals (small molecules), highlighting the importance of rs1800716 splice-disrupt variants, located on CYP2D6, in prostate cancer." (PMID 35286517, 2022). "Mutations at the genes CYP2D6 and NAT2 were analysed by allele-specific polymerase chain reaction and restriction mapping in DNA from 94 subjects with prostate cancer and 160 male healthy control subjects." (PMID 9823980, 1998).
sickle cell disease (3 papers, 2017 to 2025). Sickle cell anemias are chronic hemolytic diseases that may induce three types of acute accidents: severe anemia, severe bacterial infections, and ischemic vasoocclusive accidents (VOA) caused by sickle-shaped red blood cells obstructing small blood vessels and capillaries. "Multivariate linear regression models of CYP2D6 1934G>A and CAT -21A>T and -262C>T variants in patients with sickle cell anemia (SCA) undergoing hydroxyurea (HU) treatment." (PMID 33013391, 2020).
skin rashes (3 papers, 2012 to 2025). "In our study, the subjects with reduced CYP2D6 function were associated with an increased risk of rash in the gefitinib cohort." (PMID 23207012, 2012). "CYP2D6 phenotypes are a risk factor for the development of rash in gefitinib therapy." (PMID 23207012, 2012). "The frequency of rash was significantly higher in patients with reduced CYP2D6 activity who treated with gefitinib compared to patients with functional CYP2D6." (PMID 23207012, 2012).
tuberculosis (3 papers, 2021 to 2025). A chronic, recurrent infection caused by the bacterium Mycobacterium tuberculosis. "In this sense, 4 theses have been found to obtain the title of a pharmacist in the study carried out by Vera M.; the presence of the CYP2D6 gene with the allelic variants CYP2D6*1, *3, *4 and *6 was detected in 20 patients with tuberculosis from the city of Arequipa, Peru." (PMID 36518034, 2022). "Previous studies have reported associations between differential DNA methylation levels in promoter regions of genes encoding metabolic enzymes—such as CYP2E1, CYP2D6, GSTP1, and NAT2—and ATDILI risk in tuberculosis patients." (PMID 40133601, 2025).
acute lymphoblastic leukaemia (2 papers, 2017). "Besides genetic polymorphisms of CYP1A1, CYP2D6, GSTM1 and GSTT1 associate with acute lymphoblastic leukemia in Indian children." (PMID 28902850, 2017).
brain tumors (2 papers, 2012 to 2024). "Patients with stroke showed differences as compared to patients with brain tumors (P < 0.05), and both patients with brain tumors or with cranial nerve neuropathies differed in their CYP2D6 phenotype with regard to controls (P < 0.05)." (PMID 22482072, 2012). "Furthermore, the pursuit of therapies targeting CYP2D6 LoF could hold relevance in the realm of brain tumors." (PMID 39368455, 2024).
breast tumor (2 papers, 2017 to 2021). "Although there are discordant results described in the literature, for example the deletion of the CYP2D6 gene in breast tumor tissue is reported to cause departures from HWE23, it seems unlikely that the ESR1 gene is deleted in our study as HWE is not violated." (PMID 33547330, 2021). "We report that expression of CYP2D6 is higher in AA breast tumor samples compared to AS and CA BRCA." (PMID 28684774, 2017).
cognitive decline (2 papers, 2019 to 2025). "For instance, reduced CYP46A1 activity has been linked to amyloid-beta accumulation and cognitive decline in AD, while altered CYP2D6 expression in the basal ganglia correlates with increased susceptibility to PD." (PMID 40126262, 2025).
colon cancer (2 papers, 2016 to 2018). "Our results showed that PGRMC1 contributes to enhancement of the doxorubicin metabolism, which is mediated by CYP2D6 or CYP3A4 in human colon cancer HCT116 cells." (PMID 26988023, 2016).
colorectal adenocarcinoma (2 papers, 2021 to 2025). The most common type of colorectal carcinoma. "The ADMET of kaempferol from absorption with human colorectal adenocarcinoma cells (Caco-2), distribution using the blood–brain barrier (BBB), metabolism in CYP2D6, excretion with total clearance, and toxicity with Ames prediction." (PMID 40243778, 2025).
fibrosis (2 papers, 2016). the formation of excess fibrous connective tissue in an organ or tissue in a reparative or reactive process. "However, the Km and CLint values of CYP2D6 in the fibrosis group did not significantly differ from the control subjects." (PMID 27203676, 2016).
glaucoma (2 papers, 2023 to 2025). Increased pressure in the eyeball due to obstruction of the outflow of aqueous humor. "Various SNPs in the PTGFR, ADRB2, and CYP2D6 genes can affect the response to pharmacologic therapy in glaucoma." (PMID 40142989, 2025). "For example, among the drugs for glaucoma treatment, a major cause of legal blindness, these are timolol metabolized by CYP2D6; betaxolol, a substrate for CYP1A2 and CYP2D6; dorzolamide eliminated by CYP2B1, CYP2C9, CYP2E1, and CYP3A2; and pilocarpine, which inhibits CYP2A6, CYP2A13, and CYP2E1." (PMID 36914277, 2023).
Hepatic failure (2 papers, 2021 to 2022). "The reported pharmacokinetic study suggested that CYP2E1 was the most stable enzyme, whereas CYP2C19 (with CYP1A1 and CYP2D6 in the middle) was the most vulnerable in liver failure." (PMID 34575411, 2021). "The published clinical pharmacokinetic studies suggest that liver failure can affect CYP1A2, CYP2C19, CYP2D6, CYP2E1 and CYP3A4 activities." (PMID 34575411, 2021).